MTOR (mechanistic target of rapamycin kinase)
Diseases named in the same sentence as MTOR in open-access papers (continued):
Sharing a sentence is not in itself a finding about the gene and the disease.
tumor (continued). "This overexpression drives tumor cell proliferation by stimulating IGF1R and subsequent signaling pathways, including the PI3K/AKT/mTOR and RAS/RAF/MEK/ERK pathways, and is often associated with epigenetic changes at the 11p15 locus." (PMID 40145087, 2025). "Combining CDK4/6 inhibitors with PI3K/mTOR inhibitors can significantly slow tumor growth in animal models, suggesting that PI3K/mTOR inhibitors can help restore sensitivity to CDK4/6 inhibitors." (PMID 40303296, 2025). "In the TME, IL-15 can activate the Trx system through mTOR, increasing thiol levels on the NK cell surface to stabilize its tumor-killing capability and reverse microenvironment immunosuppression." (PMID 40847302, 2025). "Taken together, these findings suggest that knocking down APOC1 can promote apoptosis in DLBCL cells and reduce their proliferation, migration, invasion, angiogenesis, and tumor growth via the PI3K/AKT/mTOR signaling pathway." (PMID 39873475, 2025). "The inhibition of BCL6 or mTOR can reverse the resistance of tumor cells.In addition, the activation of the MAPK signaling pathway, c – MYC, etc., also contributes to the induction of tumor resistance." (PMID 39838405, 2025). "Chronic inflammatory signaling (e.g., IL-6/STAT3) and PI3K/AKT/mTOR activation contribute to an immune-excluded, myeloid-dominant tumor microenvironment (TME) and primary resistance to PD-1." (PMID 41374963, 2025). "BCAAs, particularly leucine, can activate the mTOR pathway, improving the function of immune cells such as T cells and natural killer cells, thereby boosting the anti-tumor immune response." (PMID 40438606, 2025). "Nevertheless, the senolytic effect of mTOR inhibitors still requires further exploitation and tests in more tumor types." (PMID 39811803, 2025). "One significant factor contributing to this resistance is the increased activity of growth factor signaling pathways (HER2 and the PI3K/AKT/mTOR) which can drive tumor progression." (PMID 40427153, 2025). "In fact, the PI3K/AKT/mTOR signaling cascade is crucial in driving disease progression and tumor development, and it is often activated in NSCLC." (PMID 40453647, 2025). "The dysregulation of the PI3K/AKT/mTOR pathway in tumor cells plays a pivotal role in immune evasion and tumor progression, leading to immune cell exhaustion and suppression." (PMID 40486875, 2025). "BCAA metabolism inhibits autophagy through the mTOR signaling pathway, thereby supporting the metabolic needs of tumor cells." (PMID 40438606, 2025). "TRIM7, TRIM13, and TRIM26 regulate the PI3K/AKT/mTOR pathway as tumor suppressors in kidney cancers." (PMID 40723250, 2025). "The activation of mTOR leads to the phosphorylation of S6K, which induces apoptosis and inhibits tumour growth." (PMID 40453070, 2025). "In the T cell compartment, the function of CD8+ T cells is suppressed by multiple mechanisms, including lactic acid accumulation: the high lactic acid environment produced by tumor glycolysis directly inhibits mTOR signalling and T cell function." (PMID 41555916, 2025). "ZDHHC22 has been shown as a tumor suppressor due to reducing mTOR stability via palmitoylation, decreasing AKT signaling pathway activation, and restraining breast cancer growth." (PMID 40814339, 2025). "Advances in understanding the tumour microenvironment and immune modulation guide the rational use of immunotherapy and mTOR-based immunosuppression." (PMID 41301037, 2025). "TIG1 promotes tumor cell apoptosis and reduces abnormal cell proliferation by inhibiting the mTOR signaling pathway and inducing an ER stress response." (PMID 40699636, 2025). "Concurrently, the increase in phosphorylated PTEN suggests enhanced PTEN activity, which negatively regulates the PI3K/Akt/mTOR pathway, thereby inhibiting mTOR signaling and potentially reducing tumor growth and progression." (PMID 40066708, 2025).
tumor (continued). "Recent evidence suggests that USP5 supports mTOR signaling integrity and facilitates tumor progression, consistent with our findings that suggest USP5 functions as an oncogene, enhancing tumor cell proliferation and metastasis." (PMID 40066708, 2025). "Taken together, these transgenic models highlight a distinct form of epithelial lineage plasticity driven by TFE3-fusions and implicate the critical role of mTOR signaling in MiT/TFE fusion-driven tumor types." (PMID 41044182, 2025). "Analysis of subcutaneous tumor tissues from mice demonstrated that BCKDK silencing inhibited AKT/mTOR pathway activation in vivo." (PMID 40789057, 2025). "Everolimus (RAD001), an mTOR inhibitor, in combination with AdVs enhances oncolysis in colon cancer, inhibits tumor growth, mitigates angiogenesis, and suppresses immune responses." (PMID 40927720, 2025). "Our data suggests CMTM4 is a novel regulator of the EGFR/AKT/mTOR pathway in human tumor and affects sensitivity to EGFR tyrosine kinase inhibition." (PMID 39948411, 2025). "PP2A dysfunctionality often promotes the aberrant activation of pathways, including mTOR, and the enhanced phosphorylation of own and downstream targets, such as S6 kinase, facilitating tumor growth and progression." (PMID 41146310, 2025). "The PI3K/AKT/mTOR signaling pathway is a core regulatory pathway involved in the malignant behavior of tumor cells, playing a critical role in tumor initiation and progression." (PMID 40303931, 2025). "Levels of phosphorylated mTOR, NF-κB, PD-L1 and Ki-67 (a marker of tumor proliferation) were also reduced following SLC6A14 inhibition." (PMID 41444422, 2025). "It affects the tumor microenvironment by regulating metabolic and immune-related pathways (e.g., mTOR, Wnt)." (PMID 40717587, 2025). "Immunohistochemical analysis of colorectal adenocarcinoma samples revealed elevated p-PI3K, p-AKT, and mTOR proteins in tumor tissues compared to normal mucosa." (PMID 39512697, 2024). "The metabolic reprogramming function of UL38 relies on its interaction with TSC2 (tuberous sclerosis 2), a tumor suppressor that hinders mTOR (mammalian target of rapamycin) signaling." (PMID 38720392, 2024). "In the presence of transforming growth factor-β, the PD-1-pathway-mediated downregulation of Akt/mTOR signaling induces Treg cell development, resulting in the augmentation of immunosuppressive conditions in tumor-bearing hosts." (PMID 38791040, 2024). "We assessed response to PI3K/mTOR inhibitors in immunodeficient and humanized uLMS patient‐derived xenografts (PDXs) by evaluating tumour microenvironment modulation using multiplex immunofluorescence." (PMID 38711203, 2024). "Further research in CRC has highlighted the negative correlation between miR-34 and the phosphatidylinositol 3-kinase (PI3K)/protein kinase B (AKT)/mechanistic target of rapamycin (mTOR) signaling pathway, a critical axis for tumor growth and metastasis." (PMID 39512697, 2024). "To link our in vitro transcriptomic analysis to the in vivo effect on tumor growth, we assessed the percentage of H3-K27M cells that are positive to mTOR signal (double-positive), out of the total number of H3-K27M cells, by immunofluorescence staining." (PMID 39093942, 2024). "Higher expression of Beclin1, contemporary with lower levels of mTOR gene and p62 protein lead to autophagy activation in tumor tissues." (PMID 38164366, 2024). "Pathology reports and tissue blocks were reviewed, and immunohistochemistry (IHC) was performed in order to assess the expressions of CYLD (tumor-suppressor gene) and mTOR, among other markers." (PMID 38929613, 2024).
tumor (continued). "They reported that thrombospondin 1 (which facilitates angiogenesis, tumor growth, and metastasis at the tumor site) expression was upregulated via FGF7-FGFR2b interaction through PI3K/Akt/mTOR signaling." (PMID 39766329, 2024). "For example, recent publications have identified mTOR signaling and the SEMA6A/RHOA/YAP axis as off-target mechanisms in BRAFi-associated tumor-protective effects of fibroblasts in the TME." (PMID 38839106, 2024). "ChREBP also seems involved in upregulation of glycolysis in tumor cells (Warburg effect) and acts as a proto-oncogenic mediator via Akt/mTOR, cMyc signaling, and other pathways." (PMID 39518998, 2024). "In HCC, hyperactivation of mTOR drives anabolic processes, providing the energy and biomass needed for rapid tumor growth." (PMID 39840041, 2024). "Many authors also report that dysregulation of the mTOR pathway leads to uncontrolled cell division and tumor development." (PMID 39410026, 2024). "As a result, more SLC7A5 was located in in the membrane to transport leucine, which activated the mTOR pathway and ultimately accelerated tumor growth." (PMID 38556586, 2024). "Over the past few decades, various genetic mutations, microRNAs, as well as tumor microenvironmental factors have been identified, impacting pathways like PI3K/AKT/mTOR, DNA repair mechanisms, oxidative stress, and inflammation." (PMID 38673891, 2024). "Using a CD34+ humanized PDX model representative of a metastatic pS6high uLMS, we demonstrate that pharmacological inhibition of the PI3K/mTOR pathway elicits anti‐tumour immune responses and sensitises these tumours to PD‐1 blockade." (PMID 38711203, 2024). "Our results showed significantly elevated p-mTOR levels in tumor tissues compared to NCMT (p < 0.0001), underscoring mTORC1's dominant role in OSCC." (PMID 38560690, 2024). "In lean mice, Leu promoted tumor growth by activating the mTOR signaling pathway, while, in overweight mice, Leu supplementation increased the amount of glucose available to tumor cells, further accelerating tumor growth." (PMID 39595578, 2024). "In vivo and in vitro studies demonstrated the enhanced anti-tumor activity from combining mTOR inhibitors, such as everolimus, with KRAS G12C inhibitors." (PMID 38756650, 2024). "Aberrant activation of the mTOR signaling pathway has emerged as a significant driver of tumor growth and progression, prompting considerable interest in mTOR as a target for anti-tumor drug development." (PMID 38891085, 2024). "Our studies also aimed to investigate the mTOR activity in rare tumor types, such as central nervous system tumors, childhood rhabdomyosarcoma, osteosarcoma, medulloblastoma, and fibrosarcoma." (PMID 38515456, 2024). "Continuous activation of the PI3K/Akt/mTOR signaling pathway is a typical survival mechanism in human tumor cells 5-7." (PMID 38356720, 2024). "Compared to the vehicle, the mTOR inhibitor everolimus (5 mg/kg, i.p., twice per week) significantly reduced the tumor weight and tumor volume." (PMID 38177295, 2024). "miR-21 specifically targets PTEN and PDCD4 through the PI3K/AKT/mTOR pathway to promote tumor growth." (PMID 39857631, 2024). "In PTC tissues and cells, the expression of p62 is upregulated, and knocking out p62 can inhibit tumor growth by regulating the AKT/AMPK/mTOR pathway." (PMID 39349421, 2024). "The upregulation of RTKs such as HER3, HGF/c-MET, AXL, and FGFR enhances the PI3K/AKT/mTOR anx Src pathways, promoting tumor cell proliferation." (PMID 39769140, 2024). "Independent of PIK3CA gene mutation, BKM treatment induced both the inhibition of the PI3K/AKT/mTOR pathway and initial tumor growth in xenografts." (PMID 39682182, 2024). "For example, PI3Kγ signalling in macrophages promotes immune suppression and tumour growth via Akt‐ and mTor‐mediated inhibition of NFκB and activation of C/EBPβ." (PMID 39330930, 2024). "They both target mTOR for K48 ubiquitination and are recognized as tumor suppressors in colorectal and hepatic cancers." (PMID 38534381, 2024).
tumor (continued). "During angiogenesis, PI3K/AKT/mTOR is activated in endothelial cells and these phosphorylated PI3K/AKT/mTOR generate angiogenesis factor in tumor cells, which is involved in the cell proliferation and survival." (PMID 38613124, 2024). "The concordance of studies on the expression of p-RPS6 in OED and OSCC suggests the involvement of the deregulated Akt/mTOR pathway in the early events of tumor progression and the pathogenesis of OSCC." (PMID 38370876, 2024). "mTOR is a central regulator of biological processes such as tumor growth, cell survival, metabolism, and immunity." (PMID 39596452, 2024). "Shekhar Saha and colleagues reported that DRAIC exerts its tumor suppressive function by modulating Glucose transporter 1 (GLUT1) expression to deliver signals from IKK/NF-κB to the AMPK/mTOR pathway." (PMID 39404384, 2024). "Consistent with in vitro results, we found that the reduction effect of pitavastatin on p-AKT and p-mTOR expressions in tumor tissues of CD36−/− mice was less than that in WT mice." (PMID 38319449, 2024). "Specifically, in a genetic model of papillary renal cancer triggered by Tsc2 heterozygous inactivation, Pml genetic deletion accelerated tumor progression, and this was accompanied by increased mTOR activity in the kidney." (PMID 38730056, 2024). "The mTOR signaling pathway, frequently activated in tumors, has a significant impact on tumor metabolism, cell proliferation, and immune cell differentiation." (PMID 39456230, 2024). "It uses drugs such as IGF-1R or mTOR to inhibit tumor growth in order to achieve a therapeutic effect." (PMID 39445018, 2024). "The mechanism that tumor cells use is the mutation in the myelocytomatosis oncogene (MYC) and PI3K/AKT/mammalian target of rapamycin (mTOR) signaling pathways." (PMID 38410760, 2024). "Abnormal activation of mTOR pathway leads to anabolism and energy storage, supplying a plethora of nutrients to the tumor, thus promoting tumor proliferation." (PMID 39349424, 2024). "Accumulating evidence demonstrates that EMT, PI3K/Akt/mTOR signalling pathway, and autophagy play important roles in the tumor progression, metastasis, and chemoresistance." (PMID 39084065, 2024). "Alterations in the PI3K/AKT/mTOR pathway are prevalent in hormonal breast cancer, over-activating the pathway and allowing uncontrolled tumor cell growth, resistance to apoptosis, and tumorigenesis." (PMID 39000600, 2024). "Previous studies reported that the AKT/mTOR signaling pathway was closely related to tumor proliferation and metastasis, and participated in the EMT process of tumors." (PMID 39593172, 2024). "Recently, it was demonstrated how pharmacologically targeting the mTOR complex it is possible to inhibit malignant cell growth in vitro and in vivo tumour tissues." (PMID 38459714, 2024). "Preclinical studies have demonstrated that activating LKB1-AMPK signaling can delay tumor onset and inhibit metastasis, particularly in models with hyperactive mTOR." (PMID 39682234, 2024). "Another study performed experiments in in vivo and in vitro models and found that TAMs increase the number of tumor stem cell populations by altering AKT/mTOR signaling, which leads to treatment resistance." (PMID 39169402, 2024). "Taken together, Akt/mTOR signaling is important in direct tumor progression and in human cellular and humoral immunity via the modulation of multiple immune cells." (PMID 38791040, 2024). "We show that pharmacological inhibition of the PI3K/mTOR pathway induces profound tumour microenvironment remodelling and is able to sensitise these primary resistant tumours to immune checkpoint blockade." (PMID 38711203, 2024). "In Khanom’s in vitro study, they found that K17 stimulated Akt/mTOR pathway and glucose uptake, which supports its role in tumor growth." (PMID 38891785, 2024).
tumor (continued). "Significantly, knockdown of SPOP leads to spontaneous replication stress and impaired recovery from replication fork stalling through PI3K/mTOR signaling mechanism to promote tumor progression." (PMID 39074086, 2024). "Concurrently, genes correlated with invasiveness and metabolic activity, such as E2F Targets, MYC Targets V1, and PI3K AKT MTOR Signaling, were upregulated within the tumor cells of the solid pattern samples." (PMID 38505588, 2024). "Next, in an effort to generate fresh concepts for the creation of novel tumor treatment approaches, we enumerated the signaling pathways associated with purinosomes in the control of tumor metabolism, including the AMPK, mTOR, and HIF-1 signaling pathways." (PMID 38746670, 2024). "And in terms of HALLMARK pathways, overexpressed BCAT1 was also positively associated with tumor-related and angiogenesis-related pathways, such as KRAS signaling pathway, PI3K/Akt/mTOR signaling pathway, and Angiogenesis pathway." (PMID 38309289, 2024). "Together with other kinase inhibitors such as chloroquine and mTOR inhibitors (rapamycin), they enhance apoptosis and reduce xenograft tumor size in vitro." (PMID 38523673, 2024). "The mTOR inhibitors rapamycin and everolimus have also demonstrated potential by reducing cell viability and suppressing tumor progression in both cell lines and animal models." (PMID 39590345, 2024). "AZD8055 is a recent ATP-competitive mTOR inhibitor, which has both tumour suppressing activity and induces autophagy." (PMID 38774756, 2024). "Phosphorylation of Akt generates p-Akt, which can further activate the mTOR pathway, increasing its expression, and enhances the proliferation and migration of tumor cells." (PMID 38541744, 2024). "It was also discovered that the contents of OPN, p-PI3K, p-Akt, mTOR as well as GPX4 in tumor tissues of mice in the OPN-OE group were rapidly elevated in comparison with the Vector group." (PMID 38526702, 2024). "Pathway analysis indicated that 5-HT activated the PI3K/Akt/mTOR pathway, promoting tumor metabolic reprogramming." (PMID 39385213, 2024). "The PI3K/Akt/mTOR signalling system regulates several cellular and molecular events involved in tumour genesis, invasion and metastasis." (PMID 38152044, 2024). "Studies have suggested that the mTOR signaling pathway is activated in many tumors, thereby promoting tumor growth and proliferation and inducing drug resistance." (PMID 38482057, 2024). "EVE inhibits tumor angiogenesis by directly targeting the mTOR in vascular endothelial cells, thereby suppressing their proliferation." (PMID 39736867, 2024). "Activation of the mTOR pathway in tumours was assessed using the protein extracts from tumours and analysed by western blotting." (PMID 38734930, 2024). "The effects of tacrolimus (TAC) and rapamycin (RAPA) on mTOR activity, proliferation, and tumour growth were investigated through different in vitro and in vivo experiments." (PMID 38341510, 2024). "Consistent with this conclusion, the promotion of autophagy using the mTOR inhibitor rapamycin enhanced the responsiveness of resistant tumor cells to EGFR tyrosine kinase inhibition." (PMID 39272847, 2024). "In general, our study demonstrates that FOXC1 exerts its tumor suppressor role by promoting ABHD5 transcription to regulating AMPK/mTOR signal pathway." (PMID 39093497, 2024). "Research has proclaimed that tumor cells can upregulate the PI3K/Akt/mTOR pathway, which enhances glucose uptake and aerobic glycolysis while also increasing the production of metabolites required for the synthesis of FA and cholesterol." (PMID 38357546, 2024). "Overall, our results uncovers the CBR4/FASN/mTOR axis as a mechanism for tumor development and inspires us a new molecular guide for the therapeutic strategies for GEP‐NETs treatment." (PMID 39524139, 2024).